CDKL5 (cyclin dependent kinase like 5)
Diseases named in the same sentence as CDKL5 in open-access papers (continued):
Sharing a sentence is not in itself a finding about the gene and the disease.
Cognitive impairment (12 papers, 2009 to 2025). Abnormal cognition is characterized by deficits in thinking, reasoning, or remembering. "This study reveals a novel role of CDKL5 in long-range callosal maturation and points to a causal link between functional callosal overconnectivity and cognitive impairment in NDD." (PMID 36737483, 2024). "Finally, when CDKL5 was selectively re-expressed only in this CPN subtype, in otherwise CDKL5-deficient mice, it was sufficient to prevent the cognitive impairments of CDKL5 mutants." (PMID 36737483, 2024). "These deficits were associated with significant cognitive impairments in CDKL5 KO mice." (PMID 36737483, 2024). "In parallel, it has also shown possible benefits in a variety of neurological conditions, including mild cognitive impairment, cyclin-dependent kinase-like 5 (CDKL5) deficiency, pyruvate dehydrogenase complex deficiency, Alzheimer’s and Parkinson’s disease, and many more, gaining immense popularity." (PMID 37892458, 2023). "Cyclin-dependent kinase-like 5 (CDKL5) deficiency disorder (CDD) is a severe X-linked neurodevelopmental condition characterized by early-onset, intractable epilepsy, motor and cognitive impairment, and autistic-like features." (PMID 40724873, 2025). "Mouse models of CDD recapitulate several aspects of CDD symptomology, including cognitive impairments, motor deficits, and autistic-like features, and have been useful to dissect the role of CDKL5 in brain development and function." (PMID 36982627, 2023). "In this study, we explored whether the loss of CDKL5 disrupts long-range connectivity of CPN and mediates cognitive deficits in a rodent model of CDD that faithfully recapitulates the human phenotypes." (PMID 36737483, 2024). "Although we cannot exclude that the decrease in local connectivity may also contribute to the cognitive impairments of CDKL5 KO mice, the behavioral deficits were largely recapitulated in Satb2+ conditional KOs and rescued in mice with Satb2-specific CDKL5 expression." (PMID 36737483, 2024). "Together, these results reveal a novel role of CDKL5 by demonstrating that it is both necessary and sufficient for proper CPN connectivity and cognitive function and flexibility, and further validates a causal relationship between CPN dysfunction and cognitive impairment in a model of NDD." (PMID 36737483, 2024). "This study reveals a novel role of CDKL5 by demonstrating that it is both necessary and sufficient for proper CPN connectivity and cognitive flexibility, and it also supports a causal relationship between CPN dysfunction and cognitive impairment in CDD and potentially related NDD." (PMID 36737483, 2024).
CDKL5 deficiency disorder (11 papers, 2016 to 2026). "Data on 350 individuals with a pathogenic CDKL5 variant was sourced from the International CDKL5 Disorder Database." (PMID 35978140, 2023). "For example, studies in Cdkl5-KO mouse neurons (a model for the X-linked encephalopathy CDKL5 deficiency disorder; CDD) identified neuron defects that could be restored with pregnenolone or pregnenolone-methyl-ether treatment." (PMID 34575929, 2021). "CDKL5 deficiency disorder (CDD), a severe neurodevelopmental disorder caused by mutations in the X-linked CDKL5 gene, is characterized by a complex symptomatology, including early infantile onset refractory epilepsy, hypotonia, and severe cognitive, motor, visual, and sleep disturbances." (PMID 35955854, 2022).
Anxiety (10 papers, 2018 to 2026). Intense feelings of nervousness, tension, or panic often arise in response to interpersonal stresses. "Further investigation of molecular mechanisms of enhanced anxiety and fear by the loss of CDKL5 should aid the elucidation of the pathomechanisms of mental disorders associated with excessive fear and anxiety." (PMID 29702698, 2018). "Therefore, it is possible that some C57BL/6N-specific factors or modifiers interact with functional alteration induced by the loss of CDKL5 and amplify certain phenotypes such as anxiety-like responses robustly in the KO mice." (PMID 29702698, 2018). "Consistent with previous reports on Cdkl5-KO, adult 492stop/Y mice displayed various behavioral phenotypes, including motor impairments and increased anxiety." (PMID 40042769, 2025). "These mice exhibited altered spine morphology across brain regions and behavioral deficits such as reduced sociability, impaired motor coordination, and increased anxiety, consistent with other Cdkl5 knockout models." (PMID 40042769, 2025). "We found that Cdkl5 − /Y mice spent less time in the center and more time close to the wall of the arena compared to Cdkl5 + /Y mice, suggesting increased anxiety." (PMID 39592934, 2024). "Only a trend toward an improved anxiety-related behavior, assessed using the open field test, was found in P021-treated Cdkl5 KO mice." (PMID 39592934, 2024). "Analyses of emotional behaviors revealed significantly enhanced anxiety-like behaviors of Cdkl5 -/Y mice." (PMID 29702698, 2018). "Applying the comprehensive assay strategy, we have identified the significant enhancement of anxiety- and fear- related behaviors in Cdkl5 KO mice for the first time." (PMID 29702698, 2018). "These behaviors of Cdkl5 -/Y mice indicate hypoactivity that should be derived from the enhanced anxiety in a novel environment." (PMID 29702698, 2018). "In Cdkl5 KO mice, the sum of the anxiety in a novel environment and their sociability should exceed the anxiety to an unfamiliar mouse, and drive them to stay together." (PMID 29702698, 2018). "We examined anxiety-related behaviors of Cdkl5 -/Y mice by the light/dark transition, open field, and elevated plus maze tests." (PMID 29702698, 2018). "The marked decrease in the traveled distance and center time during the first 5 minutes indicates a reduction of exploration in novel, unprotected environment, suggesting an enhancement of anxiety-like behaviors of Cdkl5 KO mice." (PMID 29702698, 2018). "The Cdkl5 exon-6-targeted KO mice have been shown to exhibit hyperactivity, decreased anxiety in a zero-maze assay, and unaltered anxiety in an open field test." (PMID 29702698, 2018). "These altered social interactions of Cdkl5 -/Y mice should be the consequence of the interaction of significantly enhanced anxiety with their sociability." (PMID 29702698, 2018). "On the one hand, a group of lines including Cdkl5−/y, Il1rapl1−/y, Ptchd1−/y, Atp6ap2Camk2a/y, Mbd5+/−, and Ehmt1+/− displayed alterations mainly in activity, repetitive behaviour, novelty exploration and anxiety (Axis 1)." (PMID 36551904, 2022). "Thus, all data from light/dark, open field, and elevated plus maze tests consistently indicate significantly enhanced anxiety-like behaviors of Cdkl5 KO mice." (PMID 29702698, 2018). "We find that our Cdkl5 KO mice exhibit significantly enhanced anxiety- and fear-related behaviors." (PMID 29702698, 2018). "In these two tests, significantly increased anxiety of Cdkl5 KO mice may be modulating the depressive-like responses, and may alter their behaviors." (PMID 29702698, 2018). "However, due to the large inter-subject variability in fear memory retention in both wild-type and Cdkl5 −/Y mice, which could depend on a variable shock sensitivity and/or anxiety state, the number of Cdkl5 −/Y runners used in this study was not sufficient to reach statistical significance." (PMID 37759796, 2023).
Anxiety (continued). "The strain-dependent modifier effects on anxiety or any other responses can give us a significant insight into the roles and the LOF of CDKL5." (PMID 29702698, 2018). "In contrast, we do not observe overactivity or anxiety in the open field test as reported in Cdkl5 models of both sexes." (PMID 38081835, 2023). "Furthermore, behavioral discrepancies were reported in calcineurin-KO, Cdkl5-/Y and PSD95-KI mice in anxiety-like behavioral tests, such as light/dark transition, open field, and the elevated plus maze test." (PMID 30359304, 2018).
Down syndrome (8 papers, 2016 to 2025). "We first confirmed the effectiveness of this method using adult C57BL/6J wild-type mice and, subsequently, we investigated a mouse model of Down Syndrome and of CDKL5 deficiency disorder, which often involves sleep-disordered breathing in humans." (PMID 40153464, 2025). "IS was present in most of the children with pathogenic variants in CDKL5 (3/4) and TSC2 (5/7) and with Down syndrome (with or without karyotype confirmation of trisomy 21) (20/22)." (PMID 29518120, 2018). "Differently from a recent study that demonstrated the effect of luteolin treatment in increasing cell proliferation in a mouse model of Down syndrome, we did not observe an increased number of Ki-67-positive cells in the hippocampal dentate gyrus of Cdkl5 KO mice." (PMID 34238328, 2021).
infantile epileptic encephalopathy (8 papers, 2014 to 2024). an epileptic condition characterized by epileptiform abnormalities associated with progressive cerebral dysfunction. "CDKL5 (cyclin-dependent kinase-like 5) Deficiency Disorder (CDD) is a rare genetic disorder characterized by severe neurologic manifestations, including infantile epileptic encephalopathy and cognitive disabilities and has been also associated with ASD." (PMID 36547476, 2022).
tuberous sclerosis complex (8 papers, 2020 to 2025). "Three infants were diagnosed with tuberous sclerosis and three others had genetic epileptic encephalopathies identified (1p36 deletion, 15q duplication, and CDKL5 mutation)." (PMID 31518001, 2020). "Beyond DS and LGS, soticlestat has been explored as a potential treatment for other DEEs, including chromosome 15q duplication syndrome, cyclin-dependent kinase-like 5 (CDKL5) deficiency disorder (CDD), and tuberous sclerosis complex." (PMID 40337521, 2025). "They include Fragile X (FXS), Cdkl5 Deficiency disorder (CDD), Cornelia de Lange syndrome (CDLS), and Tuberous Sclerosis Complex (TSC)." (PMID 37681912, 2023). "The syndrome is classified into symptomatic, idiopathic, and cryptogenic forms, based on underlying causes such as brain trauma, malformations, infections, chromosomal abnormalities (e.g., Tuberous Sclerosis Complex), or genetic mutations in genes like ARX and CDKL5." (PMID 41357344, 2025). "Around 70%–75% of cases have an identifiable cause, which can include brain trauma, malformations, infections, chromosomal abnormalities like Tuberous Sclerosis Complex (TSC), or mutations in genes like Aristaless-related homeobox (ARX) or cyclin-dependent kinase-like 5 (CDKL5)." (PMID 41357344, 2025).
fragile X syndrome (7 papers, 2021 to 2025). A genetic syndrome caused by mutations in the FMR1 gene which is responsible for the expression of the fragile X mental retardation 1 protein. "The clinical trials for ganaxolone included patients with various conditions such as Fragile X Syndrome, CDKL5 deficiency disorder, CSWS, Lennox-Gastaut, and PCDH19." (PMID 40787618, 2025). "Furthermore, neurons derived from preclinical models for prevalent monogenic conditions such as fragile X syndrome and CDKL5 deficiency disorder have recently been discovered to display defects in SV retrieval." (PMID 37648685, 2023). "In addition to CDKL5 and CACNA1E encephalopathies, increased Ca2+ influx through Cav2.3 may contribute to seizures in Fragile X syndrome, as reduced FMRP function leads to increased Cav2.3 expression." (PMID 38081835, 2023).
microcephaly (7 papers, 2015 to 2024). A congenital or acquired developmental disorder in which the circumference of the head is smaller than normal for the person's age and sex. "In conclusion, our data show that homozygous cdkl5sa21938 zebrafish recapitulate a number of characteristics of CDKL5 deficiency disorder, such as the presence of microcephaly, craniofacial dysmorphic features, and locomotor behavior defects." (PMID 35665761, 2022).
Seizure (7 papers, 2016 to 2025). A seizure is an intermittent abnormality of nervous system physiology characterized by a transient occurrence of signs and/or symptoms due to abnormal excessive or synchronous neuronal activity in the brain. "Cyclin-dependent kinase-like-5 (CDKL5) deficiency disorder (CDD) is a severe X-linked neurodegenerative disease characterised by early-onset epileptic seizures, low muscle tone, progressive intellectual disability and severe motor function." (PMID 34913468, 2022). "As reflected in our time-to-event curve, the risk of developing seizures was significantly higher in CDKL5 affected females than those with RTT during the first 20 years of age." (PMID 27080038, 2016). "CDKL5 disorder primarily affects girls and is characterized by early-onset epileptic seizures, gross motor impairment, intellectual disability, and autistic features." (PMID 29977282, 2018).
Angelman syndrome (6 papers, 2013 to 2024). A neurogenetic disorder characterized by severe intellectual deficit and distinct facial dysmorphic features. "Other forms of genetic epilepsy include Angelman’s syndrome, POLG1 mutation, CDKL5 disorder, SLC2A1 (Glut1 deficiency syndrome), ring chromosome 20, and Dup 15q syndrome, among others." (PMID 38883088, 2024). "Nevertheless, the CDKL5 variant was still suspicious due to the clinical phenotype of the patient, since the referring physician considered his disease to be consistent with Angelman syndrome, and previously ruled out UBE3A methylation and sequence defects." (PMID 24215330, 2013).
early infantile epileptic encephalopathy 2 (6 papers, 2016 to 2024). "The majority of patients with CDKL5 mutations/deletions are heterozygous females, and are diagnosed as atypical Rett syndrome, West syndrome, or early infantile epileptic encephalopathy 2 (EIEE2) (OMIM #300672)." (PMID 29702698, 2018). "For example, in contrast to MET, CDKL5, a transcription factor, is not only associated with ASD risk but also is a susceptibility locus for early infantile epileptic encephalopathy 2 (EIEE2)." (PMID 27597832, 2016).
Epileptic spasm (5 papers, 2017 to 2022). A sudden flexion, extension, or mixed extension-flexion of predominantly proximal and truncal muscles that is usually more sustained than a myoclonic movement but not as sustained as a tonic seizure. "It is uncertain what proportion of epileptic spasms are attributable to CDD, however one study identified 3 patients with pathological variants in CDKL5 among 73 patients with epileptic spasms." (PMID 35795799, 2022).
neuroblastoma (5 papers, 2017 to 2025). Neuroblastoma (NB) is the most common solid, extracranial childhood tumor. "Here, we found that CDKL5 deficiency is associated with increased ROS levels in a neuronal cell type such as the SH-SY5Y human neuroblastoma." (PMID 40076840, 2025). "Since oxidative stress is a characteristic trait of the CDD phenotype, we evaluated the effect of UBQ supplementation on oxidative stress in a human neuronal cell model of CDKL5 deficiency, the CDKL5 knockout (KO) SH-SY5Y neuroblastoma cell line (SH-CDKL5-KO)." (PMID 40076840, 2025). "Previous loss- and gain-of-function studies in SH-SY5Y neuroblastoma cells suggested that CDKL5 inhibits cell proliferation." (PMID 28740074, 2017). "CDKL5 deletion in human neuroblastoma cells induces an increase in cell death and in DNA damage-associated biomarkers." (PMID 34073043, 2021). "This would be in agreement with the observation made in neuroblastoma patients, in which high expression of CDKL5 correlates with an increased overall survival." (PMID 28740074, 2017). "However, the action of CDKL5 in tumorigenicity is definitively more complex since, at variance with neuroblastomas, in glioblastomas, CDKL5 was shown to be required for tumor cell survival and increased CDKL5 expression was found to be associated with reduced overall survival." (PMID 28740074, 2017). "The best recovery of defective phenotypes in SH-CDKL5-KO cells was obtained with the P021 dose of 10 μM, while lower concentrations (1 μM) were not effective in recovering the CDKL5-null neuroblastoma phenotype." (PMID 39592934, 2024).
Sleep apnea (5 papers, 2018 to 2025). An intermittent cessation of airflow at the mouth and nose during sleep is known as sleep apnea. "Taken together, these data support the view that CDKL5 deficiency increases the occurrence rate of sleep apneas." (PMID 39049436, 2025). "Studies on CDKL5‐knockout mice, a CDKL5 deficiency disorder model, reported sleep apneas, but it is still unclear whether these events are central (central sleep apnea) or obstructive (obstructive sleep apnea) and may be related to alterations of brain circuits that modulate breathing rhythm." (PMID 39049436, 2025). "In particular, we demonstrated that Cdkl5 -/Y adult mice showed more frequent sleep apneas compared to Cdkl5 +/Y mice, and that, at least in adult (4- to 6- month-old) mice, sleep apneas are a core feature of CDKL5 disorder and a respiratory biomarker of CDKL5 deficiency." (PMID 34094641, 2021). "Sleep apneas are more common in Cdkl5-KO than in wild-type mice." (PMID 37193389, 2022). "Furthermore, and firstly, in RTT animal studies, sleep apnea was found to be more frequent in non-rapid eye movement (NREM) sleep than in REM sleep in cyclin-dependent kinase-like 5 (i.e., Cdkl5 associates to ESV variant) mutant mouse models." (PMID 36293662, 2022). "This study aimed to categorise, for the first time, sleep apneas into CSA and OSA in CDKL5‐KO mice by simultaneously measuring ventilation and diaphragm activity during sleep." (PMID 39049436, 2025). "An abnormal breathing pattern, with a higher occurrence rate of sleep apneas, has been described in adult 4- to 6-month-old Cdkl5 KO mice, while at this age no changes in sleep pattern were observed between genotypes." (PMID 34094641, 2021). "It is not known, however, whether sleep apneas in CDKL5‐KO are CSA or OSA, and may be driven by alterations of brain circuits modulating breathing rhythm, such as the preBötC neurons expressing NK1Rs and SST." (PMID 39049436, 2025).
autism spectrum disorder (4 papers, 2018 to 2025). A spectrum of developmental disorders that includes autism, and Asperger syndrome. "LRRC4C is also phosphorylated by autism spectrum disorder vulnerability gene CDKL5, which modulates the interaction of LRRC4C with PSD-9570." (PMID 30410030, 2018).
Lennox-Gastaut syndrome (4 papers, 2020 to 2026). Lennox-Gastaut syndrome (LGS) belongs to the group of severe childhood epileptic encephalopathies. "Multiple ASM use in the present study emerged as a significant factor influencing QOL, as for CDKL5 deficiency disorder, Dravet and Lennox-Gastaut syndromes, and SCN8A." (PMID 41533235, 2026). "Overall, the data suggest that ganaxolone is efficacious in reducing seizure frequency in a variety of disorders, including CDKL5, Lennox-Gastaut syndrome, and PCDH19 patients." (PMID 40787618, 2025).
channelopathies (3 papers, 2019 to 2025). "Altogether, our findings indicate a CDKL5 role in the regulation of ion channels’ activity, supporting prior studies stating that CDD is in part a channelopathy." (PMID 40649845, 2025).